NSMAF (neutral sphingomyelinase activation associated factor)
Description:
Couples the p55 TNF-receptor (TNF-R55 / TNFR1) to neutral sphingomyelinase (N-SMASE). Specifically binds to the N-smase activation domain of TNF-R55. May regulate ceramide production by N-SMASE.
Synonyms: FAN; GRAMD5
Tractability: PROTAC: ubiquitination databases record sites on it; its protein half-life has been measured.
Gene: Protein-coding gene on chromosome 8 (58,583,504 to 58,659,959, reverse strand). Ensembl gene ENSG00000035681.
Subcellular location (Human Protein Atlas): Nucleoli
Pathways (Reactome):
Signal Transduction: TNFR1-mediated ceramide production
Gene Ontology:
Molecular function: protein binding; sphingomyelin phosphodiesterase activator activity
Biological process: ceramide metabolic process; signal transduction; tumor necrosis factor-mediated signaling pathway
Cellular component: cytoplasm; cytosol
Genetic constraint (gnomAD): Loss-of-function variants: 59 observed, 93.19 expected, observed/expected ratio (o/e) 0.63, 90% interval 0.51 to 0.79. The upper end of that interval is the gene's LOEUF score, 0.79, which puts it in group 3 of 6, group 1 being the genes least tolerant of losing a copy. Missense variants: 808 observed, 913.06 expected, observed/expected ratio (o/e) 0.88, 90% interval 0.83 to 0.94. Synonymous variants: 291 observed, 326.29 expected, observed/expected ratio (o/e) 0.89, 90% interval 0.81 to 0.98.
Homologues: Orthologues: macaque NSMAF (99% identical), chimpanzee NSMAF (98% identical), rabbit NSMAF (95% identical), dog NSMAF (94% identical), rat Nsmaf (93% identical), mouse Nsmaf (92% identical), pig NSMAF (91% identical), guinea pig NSMAF (88% identical), tropical clawed frog nsmaf (71% identical), zebrafish nsmaf (70% identical), Caenorhabditis elegans wdfy-3 (27% identical), Caenorhabditis elegans sel-2 (26% identical). Paralogues in human: NBEAL2 (31% identical), NBEAL1 (30% identical), LRBA (29% identical), NBEA (28% identical), WDFY3 (28% identical), WDFY4 (27% identical), LYST (25% identical).
Diseases named in the same sentence as NSMAF in open-access papers:
NSMAF is named in the same sentence as 8 diseases in open-access papers, as found by Europe PMC text mining. Sharing a sentence is not in itself a finding about the gene and the disease. The quoted sentences say what the papers report.
cardiac ischemia (1 paper, 2023). "Additionally in the right ventricle, we observed hypermethylation of one CpG annotated to the neutral sphingomyelinase activation associated factor gene (NSMAF), which may play a role in activation of neutral sphingomyelinase in response to cardiac ischemia or reperfusion injury." (PMID 37415206, 2023).
multiple sclerosis (1 paper, 2017). A progressive autoimmune disorder affecting the central nervous system resulting in demyelination. "Interestingly, NSMAF is also associated with multiple sclerosis, and one study demonstrated that FAN can promote melanoma cellular motility and tumour invasiveness in an in vivo model." (PMID 29115933, 2017).
NSMAF also shares sentences with these, for which no sentence is quoted: tumor (2 papers); colorectal cancer (1); COVID-19 (1); leprosy (1); renal cell carcinoma (1); Tendinopathy (1).